TNF (tumor necrosis factor)
Diseases named in the same sentence as TNF in open-access papers (continued):
Sharing a sentence is not in itself a finding about the gene and the disease.
autoimmune disease (continued). "Therefore, the balance between proinflammatory (IL-2, IFN-γ and TNF) and regulatory (IL-4, IL-10 and TGF-β) cytokines probably determines any predisposition to develop autoimmune disease." (PMID 16759382, 2006). "This review summarizes the diverse microbial strategies to regulate TNF and how such insights into TNF modulation could benefit the treatment of inflammatory or autoimmune diseases." (PMID 16518473, 2006). "We have a long-standing interest in the adjuvant effect of lipopolysaccharide (LPS) on the development of autoimmune disease, but only recently has LPS been shown to mediate its effects in part by increasing TNF-α, IL-1β, and IL-18 levels through TLR4 signaling." (PMID 15550215, 2004). "Therefore, TNF inhibitors (TNFi) are used to treat autoimmune diseases." (PMID 41346622, 2025). "Similarly, TNF-α inhibitors, which have been widely used in autoimmune diseases, may offer cardioprotective benefits in polytrauma patients by reducing endothelial dysfunction, leukocyte infiltration, and myocardial fibrosis." (PMID 40710793, 2025). "Interestingly, higher TNF levels, which are typical for autoimmune diseases, inhibit the conversion from the DHEAC to the DHEA, which may induce disequilibrium between anti- and pro-inflammatory factors (see review)." (PMID 40076462, 2025). "In both cases, the clinicians could not determine whether the TNF inhibitor or the associated autoimmune disease was the precipitating factor." (PMID 38229275, 2024). "Previous studies have indeed shown that a spontaneous, multisystem autoimmune disease developed in aging (>20 weeks) hFcγRIIa transgenic mice, and most had antihistone antibodies and antinuclear antibodies (ANAs) above background levels with elevated levels of TNF-α." (PMID 39281679, 2024). "Also, miR-23b (from the same cluster) has been shown to regulate the expression of μ-opioid receptors and to be underexpressed in various autoimmune diseases via suppressing interleukin 17 (IL-17), tumor necrosis factor α (TNF- α), or IL-1β-induced NF-kB activation." (PMID 39273498, 2024). "It was shown that rCpstefin had a potential modulatory effect on macrophage inflammation, which suggested that rCpstefin could be further applied to the study of autoimmune diseases characterized by a significant increase in IL-1β, IL-6, and TNF-α, such as inflammatory bowel inflammation." (PMID 38792680, 2024). "Compared to the DSC-EV group, the DSC-IL-6i group exhibited higher levels of TNF-α, a representative inflammatory cytokine secreted by Th1 cells, and Granulocyte-macrophage colony-stimulating factor (GM-CSF), which contributes to the pathogenicity of Th17-mediated autoimmune diseases." (PMID 38726369, 2024). "Furthermore, type 1 diabetes (DM1) is an autoimmune disorder characterized by a chronic inflammatory response common to periodontitis, with increased secretion of proinflammatory cytokines, including IL-1, IL-8, IL-6κ, and tumor necrosis factor-α." (PMID 38727455, 2024). "Although, steroids may decrease TNFα synthesis, we do not have information about targeted therapies such as TNF receptor blocking, while few cases in the literature are diagnosed with MOGAD while on anti-TNF treatment due to preexisting other autoimmune diseases." (PMID 36925938, 2023). "Furthermore, several researchers have reported the role of anti-TNF-α agents in the development of different serious side effects, including infections, malignancies, autoimmune diseases, in particular systemic lupus erythematosus, Guillain–Barre syndrome and multiple sclerosis." (PMID 36836166, 2023). "Interestingly, TNF-antagonists used for the therapy of autoimmune disorders may be viable therapeutics to reduce BPH incidence in patients with autoimmune diseases and decrease localized inflammation within the prostate." (PMID 37047137, 2023).
autoimmune disease (continued). "Furthermore, the biological functions of cytokines such as interleukin-6 (IL-6), type 1 interferon (IFN), and tumor necrosis factor-alpha (TNF-α), which constitute the cytokine storm, have been elucidated by research and clinical practice in autoimmune diseases." (PMID 36609472, 2023). "Therefore, TNF-α and IL-6 are well known to be related to autoimmune diseases such as rheumatism." (PMID 36039384, 2022). "Finally, since CD16+ monocytes are increased in several inflammatory and autoimmune diseases and possess a more mature phenotype, we explored whether IVIg also affected the in vivo expression of TNF in the distinct monocyte subsets." (PMID 35486340, 2022). "Interestingly, CXCL10 release, identified in this investigation as a robust marker of TLR7/8 immune activation, has also been shown to be part of an amplification feedback loop driven by IFNγ and TNFα release from Th1 lymphocytes in a variety of autoimmune diseases." (PMID 35261923, 2022). "Ever since the discovery of TNF-α, it has been comprehensively studied for its involvement in acute and chronic inflammation, cell differentiation and proliferation, stimulation of programs of cellular suicide including apoptosis and necroptosis, cell metabolism, autoimmune diseases and cancer." (PMID 35205024, 2022). "In addition to TNF-α, other factors are also involved in the pathogenesis of autoimmune diseases." (PMID 35655291, 2022). "Cytokines such as tumor necrosis factor alpha (TNFα), interleukin-1 (IL-1β) and interleukin-6 (IL-6) are pro-inflammatory and play central role in inflammation of which IL-6 is the most important in chronic inflammatory and autoimmune diseases, cytokine storm and cancer." (PMID 35487926, 2022). "MAPKs can positively regulate the production of inflammatory mediators such as tumor necrosis factor, interleukin-1β, and IL-6, and their impact in T cell development and activation have also been well reported, implicating MAPKs can play a role in the pathogenesis of autoimmune disease." (PMID 36309313, 2022). "Previous studies have shown that both CD14+ and CD14dim monocytes can produce cytokines TNF‐α, IL‐1β, and type I interferon under various conditions such as infection, inflammatory and autoimmune diseases, and cytokine‐release syndrome, though different signaling pathways may be involved." (PMID 35347900, 2022). "Likewise, in the treatment of autoimmune disease, TNF-alpha inhibitors are at the center, but given the progression of targeted drug development these drugs may be replaced by alternative agents with their own set of risks." (PMID 36672607, 2022). "In addition, KEGG analysis in this study showed that differentially expressed cytokines and inflammatory mediators were mainly involved in the TNF signaling pathway, which is crucial in TNF-induced cell death and is important target for the treatment of autoimmune diseases." (PMID 36389787, 2022). "An imbalance between pro-inflammatory TNF-α and anti-inflammatory IL-10 in plasma has been considered a biomarker of suppression of Th1 cell-mediated immunity and exacerbation of Th2 humoral immune response, potentially leading to the development of allergic and autoimmune diseases." (PMID 35448433, 2022). "Aberrant Th1 and Th17 cells could activate innate immune cells by producing proinflammatory cytokines, such as IFNγ, IL-17, and TNFα, and metformin is shown to inhibit in the production of cytokines of Th1 and Th17 cells, alleviating the autoimmune diseases including various ALIs." (PMID 34959222, 2021). "Furthermore, suppressing TNF-α induces a decrease in IL-1 and IL-6, along with adhesion molecules and vascular endothelial growth factors (VEGFs), and TNF blockers are being recommended for use in hospitalized patients with absurd inflammatory reactions in disorders such as autoimmune diseases." (PMID 34066983, 2021).
autoimmune disease (continued). "In addition, IL-27 can also increase the content and ratio of Th1 and Th17 cells, thus leading to the excessive secretion of inflammatory mediators in local tissues, such as IFN-γ, CXCL10, and TNF-α, Thereby forming an inflammatory cascade that eventually induces autoimmune diseases." (PMID 34691022, 2021). "Indeed, genome-wide association studies identified a single nucleotide polymorphism (SNP) in the TNFRSF1A gene coding for TNFR1 that is associated with MS but not with other autoimmune diseases, where anti-TNF therapy is working." (PMID 34305946, 2021). "Therefore, TNF-α and IL-6 are related to a wide range of inflammatory or autoimmune diseases." (PMID 34888304, 2021). "Pc-ALCL may be induced in patients receiving various immunomodulatory drugs, such as the tumor necrosis factor (TNF) blocker adalimumab used to treat various autoimmune diseases, and fingolimod, used to treat patients with relapsing-remitting multiple sclerosis." (PMID 34572893, 2021). "Towards this, we also noticed significantly increased systemic levels of TNF-α in IC mice, an observation that supports the previous finding that miRs-146 expression is the regulator of pro-inflammatory cytokines during chronic inflammatory or autoimmune diseases." (PMID 34335632, 2021). "However, the association of SNP at the TNF-α -308G/A with autoimmune diseases such as AS, RA, and PsA has not been fully elucidated." (PMID 35126146, 2021). "TNFSF13, a tumor necrosis factor, plays a significant role in tumor development and autoimmune diseases, and hypoxia promotes the retention of the intron of TNFSF13 and suppresses the spliced isoform in MCF7 cells, which may contribute to a tumor suppressor effect." (PMID 34722250, 2021). "Based on the hypothesis that excessive TNF-α accumulation may cause deleterious effects, a variety of treatments targeting TNF-α (such as Infliximab, Etanercept, Certolizumab pegol, Adalimumab) have been introduced in autoimmune diseases and have shown favorable performance." (PMID 35126146, 2021). "The T helper 1 (TH1) cells secrete IFN-γ, TNF-α, IL-2, IL-8 and mediate cellular immunity, activate macrophages to kill intracellular pathogens, and play an important role in immune regulation in the induction of organ-specific autoimmune diseases and anti-infective immunity." (PMID 33639877, 2021). "Despite the clinical success of anti-TNF therapeutics they also show limitations, such as their restricted responsiveness, and severe side-effects, such as opportunistic infections, invasive fungal infections, reactivation of tuberculosis, and development of other autoimmune diseases and lymphomas." (PMID 32528961, 2020). "Although the clinical relevance of IFN activity remains unclear, it may be that a predominance of TNF over IFN activity or vice versa may promote the development of autoimmune diseases where excess of one cytokine plays a dominant role such as in RA and SLA respectively." (PMID 32483203, 2020). "In addition, both NF-κB and TNF-α are consistently stimulated in patients with autoimmune diseases." (PMID 32059381, 2020). "Therefore, anti-TNF-alpha agents used in CD could modify concomitant autoimmune disease outcome or even may protect against them." (PMID 33042019, 2020). "LPS stimulates the secretion of proinflammatory cytokines by macrophages such as TNF-á and IL-6 which are critical to the initiation of the inflammatory response; however, hypersecretion of proinflammatory cytokines ultimately result in inflammatory-related diseases or autoimmune diseases." (PMID 30909606, 2019). "Long-term anti-TNF therapy may increase Tregs in AS and other autoimmune diseases." (PMID 31772947, 2019). "Therefore, it is likely that anti-TNFα therapy for different human autoimmune diseases may have dichotomous effects on the function of nTregs versus iTregs." (PMID 29725328, 2018).
autoimmune disease (continued). "Patients with autoimmune diseases could be genetically prone to develop another autoimmune disease, a fact that might predispose them to CNS demyelination regardless of anti-TNF-α use." (PMID 28337644, 2017). "Consequently, anti-TNF therapy has become mainstay treatment for autoimmune diseases." (PMID 28785220, 2017). "This could be interesting in the context of autoimmune disease, because modulation of the IL-20R axis might not result in the increased risk of infection seen with targeting other inflammatory mediators, such as TNFα." (PMID 26968800, 2016). "Importantly, FK506 may suppress the function of T cells via calcineurin inhibition and may also directly suppress the production of a variety of T-cell-triggered cytokines such as IFN-γ, IL-17, TNF-α and IL-1β in several autoimmune diseases." (PMID 27501378, 2016). "By meta-regression, we observed a significant negative linear relationship between duration and effect size of marine-derived n-3 PUFAs supplementation on IL-6 and TNF-α in subjects with chronic non-autoimmune disease, indicating that longer duration of use could lead to a greater lowering effect." (PMID 24505395, 2014). "In addition, IL-8 and TNF-α play an important role in the development of cellular- mediated immune response and inflammatory reaction, and they also contribute to the development of autoimmune disease." (PMID 24391778, 2013). "The inverse relationship between TNF-α and the pro-inflammatory cytokine interferon may promote immune cell activation, autoantibody formation, and immune complex deposition, eventually leading to the development of autoimmune disease." (PMID 23522744, 2013). "On the other hand, B-cell-activating factor (BAFF), a member of the tumor necrosis factor-alpha (TNF-α) family that plays crucial roles in B-cell differentiation, survival, and immunoglobulin secretion, is considered to be associated with the development of autoimmune disorders." (PMID 22988469, 2012). "The vaccine is contraindicated in individuals taking anti-tumor necrosis factor alpha (anti-TNF) therapies or other biologics commonly used to treat autoimmune diseases because of the safety concern that zoster vaccine may be associated with a short-term HZ risk." (PMID 22024532, 2011). "However, TNF-α is also associated with excessive inflammation and immunopathology in infections and autoimmune diseases, and specifically, TNF-a has been suggested to be involved in breakage of the blood-brain barrier during development of hematogenous pneumococcal meningitis." (PMID 18796140, 2008). "It has been postulated that OCD may be a manifestation ofpoststreptococcal autoimmunity, and it is known that individualswith autoimmune pathology or systematic autoimmune diseases oftenexhibit increased production of proinflammatory cytokines such asIL-6 and TNF-α." (PMID 17497035, 2007). "In contrast, gene module scores for the IFN-α, IFN-γ, and TNF response pathways were similar among VEXAS and other autoimmune diseases." (PMID 40394087, 2025). "Pro-inflammatory cytokines such as IL-6, TNF-α, and BAFF are upregulated in multiple autoimmune diseases, making them valuable for monitoring disease activity but less reliable for differentiating between conditions." (PMID 40095875, 2025). "TNF antagonists, neutralizing TNFR1-NF-κB signaling, positively affect inflammatory and autoimmune diseases." (PMID 40658178, 2025). "Contrary to findings in autoimmune disease and cancer, the blockade of LAG-3 increased the production of Th1-type tumor necrosis factor (TNF)-α and interferon (IFN)-γ, but decreased Th2-type and Treg-type IL-4, IL-10 and transforming growth factor (TGF)-β1." (PMID 41023624, 2025). "Inflammatory cytokines such as tumor necrosis factor-alpha (TNF-α), interleukin-1 beta (IL-1β), and interleukin-6 (IL-6) are elevated in many autoimmune diseases and contribute to the inflammatory milieu." (PMID 39856066, 2025).
autoimmune disease (continued). "Studies have shown that LDGs play a pro-inflammatory role in autoimmune diseases by inducing T cells to produce inflammatory cytokines, such as interferon-gamma (IFN-γ) and tumor necrosis factor-alpha (TNF-α)." (PMID 40689395, 2025). "This previous study demonstrated that NK cells secrete various cytokines and chemokines such as IFN-γ, TNF-α and CCL5, contributing to the progression of autoimmune diseases by stimulating autoreactive T and B cells." (PMID 41343465, 2025). "It is well documented that in autoimmune diseases, ABCs can exhibit unique cytokine profiles distinct from other B cells, including the production of pro-inflammatory mediators like IL-6, IFN-γ, and TNF-α." (PMID 40917658, 2025). "It specifically targets and inhibits tumor necrosis factor alpha (TNF-α), a pro-inflammatory cytokine involved in the pathogenesis of various autoimmune diseases." (PMID 39364047, 2024). "Activated T-cells and macrophages are the primary producers of TNF-α in response to inflammation and infection and inhibition of TNF-α has proven successful in the treatment of many autoimmune disorders." (PMID 38396958, 2024). "Recently, TNF and JAK inhibitors, previously proven to treat many dermatological and autoimmune diseases, were applied to CA patients to evaluate the promise and perils of these classes of drugs." (PMID 38335182, 2024). "Tumor Necrosis Factor-alpha (TNF-α): TNF-α is a potent pro-inflammatory cytokine, playing a central role in chronic inflammation and autoimmune diseases." (PMID 39683427, 2024). "Current strategies that target cytokines (e.g., tumor necrosis factor (TNF)-α), or signaling molecules (e.g., Janus kinase (JAK)) have advanced the management for allergies and autoimmune diseases." (PMID 38831367, 2024). "Plasma proteins with positive correlation with AS in this study were TNF, FKBPL, AGER, and ALDH5A1.TNF is a crucial cytokine playing a key role in the human immune response, involving various inflammatory and autoimmune diseases in their onset and development." (PMID 38566994, 2024). "Studies have found that tumor necrosis factor (TNF) and interleukin-6 (IL-6) are over-activated in autoimmune diseases and CKD." (PMID 38533318, 2024). "This astonishing power to fight invaders, however, comes at the cost of risking IFN-I-related pathologies, such as observed during autoimmune diseases, during which IFN-I and TNFα response dynamics are dysregulated." (PMID 38596672, 2024). "Next, using biologicals used for treating autoimmune diseases [i.e., anti-TNFα, and JAK inhibitors], we unraveled the crosstalk between IFN-I and TNFα signaling dynamics." (PMID 38596672, 2024). "The lymphocyte stimulating factor (BLyS) is a new member of the tumor necrosis factor (TNF) family, which has a unique role in B cell development/differentiation and autoimmune disease." (PMID 38831887, 2024). "In the mechanisms studies based on iPSCs, it is demonstrated that the pro-inflammatory cytokines such as TNF-α, IL-1β, and IFN-γ are the cores for driving disease progression in autoimmune diseases." (PMID 38720903, 2024). "Studies have indicated that the expression of tumor necrosis factor-alpha (TNF-α), interferon-gamma (IFN-γ), and several interleukins (such as IL-1, IL-6, IL-12, and IL-17) is elevated in autoimmune diseases, driving inflammation and tissue damage." (PMID 39104791, 2024). "Overall, cytokines, such as Tumor Necrosis Factor-alpha (TNF-α) and Interferon-alpha (IFN-α), modulate ferroptosis in different ways, contributing uniquely to the pathogenesis of autoimmune diseases." (PMID 37840106, 2023). "However, although a decrease in thyroid dysfunction has been reported in autoimmune disease patients treated with TNF inhibitors, we cannot draw conclusions from our study since it is unknown whether TNF inhibitor therapy was received before or after AITD onset." (PMID 36810111, 2023).